FGF23 (fibroblast growth factor 23)
Diseases named in the same sentence as FGF23 in open-access papers (continued):
Sharing a sentence is not in itself a finding about the gene and the disease.
Insulin resistance (continued). "Furthermore, FGF23 induces oxidative stress and cellular senescence in human mesenchymal stem cells from skeletal muscle, a mechanism potentially contributing to insulin resistance [31▪,44]." (PMID 40237064, 2025). "The study highlighted a significant relationship between insulin resistance and FGF-23." (PMID 39879508, 2025). "They claimed that insulin resistance-related hyperinsulinism and/or low 1.25(OH)(Vit)D3 levels may lead to a decrease in FGF-23 generation and serum levels." (PMID 39879508, 2025). "For obese adolescents, an inverse correlation of FGF-23 and insulin resistance was determined." (PMID 36437429, 2023). "FGF23 is associated with inflammation through IL-6 (interleukin 6), IL-10 (interleukin 10), and CRP (C-reactive protein) and with symptoms of metabolic syndrome: insulin resistance, visceral obesity, and dyslipidemia." (PMID 38139126, 2023). "At present, it is unclear whether acidosis-induced insulin resistance may influence the reduction of FGF23 observed in acidotic rats." (PMID 35268016, 2022). "Reduced blood Klotho concentration is associated with increased albuminuria.Klotho levels were correlated with FGF23, vitamin D, and insulin resistance, suggesting that Klotho levels might be affected by renal function." (PMID 35626360, 2022). "In addition, increased FGF-23 concentrations promote inflammation, erythropoiesis, left ventricular hypertrophy and insulin resistance." (PMID 36145151, 2022). "Interestingly, FGF23 concentrations have been connected with the occurrence of insulin resistance (IR) as well as inflammatory state, dyslipidemia, and visceral adiposity." (PMID 31847236, 2019). "In addition, few reports have analyzed insulin resistance and FGF23 while including leptin and ghrelin." (PMID 30228288, 2018). "Data on FGF23 and insulin resistance from animal models are ambiguous." (PMID 30228288, 2018). "Accordingly, insulin resistance in DM patients may inhibit the influx of phosphate and elevate serum phosphate levels, thus increasing serum FGF23 levels to normalize serum phosphate levels." (PMID 30228288, 2018). "In addition, the associations of leptin, osteocalcin (OC), fibroblast growth factor 23 (FGF23), sclerostin (Scl) and insulin resistance index (HOMA-IR) with bone biopsy results were investigated." (PMID 28719612, 2017). "Whether FGF23 induces insulin resistance should be further addressed." (PMID 35216490, 2022). "Insulin, homeostatic model assessment-insulin resistance (HOMA-IR), FGF-23 levels, CIMT, left ventricular (LV) mass, LV mass index and myocardial performance index (MPI) were significantly higher in the GDM group." (PMID 30462803, 2018). "This study aimed to examine the relationship between insulin resistance and FGF-23 and s-KL in patients with non-diabetic pre-dialysis patients with CKD." (PMID 39879508, 2025). "A significant relationship, independent of serum P levels, was observed between insulin resistance and FGF-23 levels." (PMID 39879508, 2025). "First, as the study was conducted using a cross-sectional design, the temporal results of the relationship between insulin resistance and FGF-23 in patients with CKD were not examined." (PMID 39879508, 2025). "This study aimed to examine the relationship between insulin resistance and FGF-23 and s-KL levels in patients with non-diabetic pre-dialysis CKD." (PMID 39879508, 2025). "Insulin reduces FGF-23 so, in T1DM, low insulin leads to high levels while, in T2DM, insulin resistance may reduce them." (PMID 39941397, 2025). "Therefore, we aimed to investigate the relationship between insulin resistance and FGF-23 levels in patients with non-diabetic pre-dialysis CKD." (PMID 39879508, 2025).
calcification (47 papers, 2012 to 2026). Process by which organic tissue becomes hardened by the physiologic deposit of calcium salts. "Many epidemiological studies have demonstrated that elevated levels of FGF23 are associated with renal function declining, increased cardiovascular morbidity and mortality, and higher aortic and coronary calcification scores." (PMID 35204586, 2022). "We recently reported that low levels of GRP were strongly associated with increased vascular calcification, pulse pressure and increased levels of the calcification promotors P, FGF-23 and CaxP, in this same patient cohort." (PMID 35204586, 2022). "A novel aspect of this study was the comprehensive assessment of the association of arterial calcification with bone mineral markers including FGF23, sKl, phosphate and PTH." (PMID 28870151, 2017). "FGF23 levels are associated with arterial stiffness and vascular and valve calcification, which may help us explain its harmful effects on the cardiovascular system." (PMID 32257685, 2020). "In such cases, abnormal calcium or phosphorus metabolism may also be involved in vascular calcification, in association with FGF23 or 25-hydroxyvitamin D3." (PMID 23302066, 2013). "Vascular calcification, linked to bone mineral metabolism disorders such as elevated serum phosphate, parathyroid hormone (PTH), and FGF23, well-known uremic toxins, aggravate this risk." (PMID 40559875, 2025). "In contrast to FGF-23, an inverse correlation was found between the Klotho level and arterial calcification [pooled r = − 0.388 (− 0.578 to − 0.159), p = 0.001]." (PMID 38459119, 2024). "In patients with CKD undergoing hemodialysis, FGF23 promotes peripheral vascular and aortic calcification, in addition to carotid atherosclerosis." (PMID 40115543, 2024). "The presence of abdominal aortal calcification (P = 0.001) and coronary artery calcification (P = 0.038) were also higher in the low Klotho/FGF23 ratio quartiles." (PMID 35872753, 2022). "Existing studies have shown that malnutrition and microinflammatory state, insulin resistance, FGF23/klotho axis abnormalities, and other factors are interconnected and ultimately jointly promote the occurrence of vascular calcification." (PMID 34367315, 2021). "In the future, additional investigations are warranted to further clarify the precise mechanisms by which FGF23 contributes to the development of vascular calcification." (PMID 23339433, 2013). "The main pathogenesis of vascular calcification and bone abnormalities in CKD can be explained by phosphate retention, increase in fibroblast growth factor-23 (FGF-23), and loss of calcium balance, and FGF-23 is suggested to be a pro-inflammatory cytokine." (PMID 37878613, 2023). "In phase 2, the significant reductions of iPTH, FGF-23, tartrate-resistant acid phosphatase 5b, and slightly decreased size of parathyroid gland and stabilized vascular calcification were observed at 24-week follow up and markedly rebounded after discontinuation of cinacalcet." (PMID 31014177, 2019). "In addition, AIF-1 could mediate elevations in serum phosphorus, FGF23, PTH, and vascular CCR2 as demonstrated in the present study, which was previously thought to be pathways of NF-κB causing vascular calcification." (PMID 35937793, 2022). "Hence, indirect effects of FGF23 via pro-inflammatory cytokines might additionally be at play in uremic vascular calcification." (PMID 33441772, 2021). "Therefore, the ability of etelcalcetide to better maintain mineral homeostasis, while decreasing FGF23 is crucial for the prevention of vascular calcification in this model and may suggest a safe way of lowering FGF23." (PMID 29038882, 2017). "In contrast to these favorable changes, inulin had insignificant effect on FGF23 levels but there was still a reduction in LVH and aorta/cardiac calcification." (PMID 38130753, 2023).
calcification (continued). "α-Klotho and fibroblast growth factor 23 (FGF-23) are emerging factors in CKD-MBD and are thought to be involved in the pathogenesis of vascular calcification." (PMID 30906591, 2019). "Vascular immunoreactivity for FGF23 was also significantly increased in patients with vascular calcification as compared to patients without calcification and to controls." (PMID 31542779, 2019). "Therefore, long, randomized-intervention studies are required to clarify the effect of non-calcium containing phosphate binders on changes in both FGF23 and vascular calcification in CKD." (PMID 23339433, 2013).
end-stage renal disease (42 papers, 2009 to 2025). "According to research, FGF23 is associated with end-stage renal disease and acute kidney damage, severe infections and inflammation, and even cancer progression, which is considered a possible cause of death in people with CKD." (PMID 36457804, 2022). "Most of the studies have shown a strong and independent association between FGF-23 concentrations and greater risk of end-stage renal disease in advanced-stage CKD patients, thereby making it an independent risk factor for mortality in this population." (PMID 34065223, 2021). "Using machine learning methods to analyze the risk factors of CKD-MBD in patients with end-stage renal failure, we have found that elevated serum FGF23 levels in patients with ESRD is an independent risk factor for abdominal aortic calcification." (PMID 34759797, 2021). "Meanwhile, LPA can also increase fibroblast growth factor-23 (FGF23) in acute and chronic kidney injury levels to promote chronic fibrosis, which is closely associated with subsequent CKD and end-stage renal disease." (PMID 35783860, 2022). "The previous research results of our work show that patients with end-stage renal failure have abnormal levels of FGF23 and klotho and microinflammatory states." (PMID 34367315, 2021). "In macrophages, CYP27B1 activity is also suppressed by FGF23, and in serum from patients with end-stage renal failure, who have very high FGF23 concentrations, stimulated CYP27B1 expression and calcitriol synthesis are reduced relative to serum from healthy donors." (PMID 40565034, 2025). "Our previous work identified abnormal FGF23 and Klotho levels, inflammatory status, and malnutrition were the unconventional risk factors for vascular calcification and CKD-MBD in patients with end-stage renal failure." (PMID 34759797, 2021). "In the beginning of CKD, FGF-23 attenuates vascular calcification, preventing an increase in serum phosphate levels, while FGF-23 is unable to sustain normal phosphate levels in end-stage renal disease." (PMID 34054588, 2021). "Several studies have shown that phosphate binders reduces FGF-23 levels in patients with CKD and end-stage renal disease." (PMID 29291028, 2017).
X-linked hypophosphatemic rickets (41 papers, 2007 to 2026). "Burosumab, a monoclonal antibody to fibroblast growth factor 23 (FGF23), is effective for X-linked hypophosphatemic rickets (XLH)." (PMID 41035763, 2025). "X-linked hypophosphatemic rickets (XLH) is a rare genetic disease characterized by inappropriately elevated circulating fibroblast growth factor 23 (FGF-23) and subsequent urinary phosphate wasting." (PMID 39156019, 2024). "X-linked hypophosphatemic rickets (XLH) is a genetic disorder characterized by elevated fibroblast growth factor 23 (FGF23), resulting in renal phosphate wasting and inadequate bone mineralization." (PMID 37954837, 2023). "Burosumab is a monoclonal anti-FGF23 antibody used to treat patients with X-linked hypophosphatemic rickets (XLH)." (PMID 37109242, 2023). "Mouse studies have suggested that enhanced FGF receptor (FGFR) signaling is involved in the overproduction of FGF23 in PHEX-deficient X-linked hypophosphatemic rickets (XLH) and DMP1-deficient autosomal recessive hypophosphatemic rickets type 1." (PMID 36246908, 2022). "X-linked hypophosphatemic rickets (XLH) is characterized by increased circulating fibroblast growth factor 23 (FGF23) concentration caused by PHEX (NM_000444.5) mutations." (PMID 35654784, 2022). "Burosumab (Crysvita®), developed as an anti-FGF23 (fibroblast growth factor 23) mAb by Kyowa Kirin, was approved for treating X-linked hypophosphatemic rickets in 2018 by the FDA." (PMID 35884906, 2022). "Currently, these antibodies have only been validated for the treatment of X-linked hypophosphatemic rickets caused by high plasma levels of FGF-23." (PMID 33767635, 2021). "Similarly, the administration of a modified anti-FGF23 antibody (burosumab) in patients with X-linked hypophosphatemic rickets, a disease with constantly elevated FGF23 levels, also led to elevated serum phosphate and 1,25(OH)2D levels." (PMID 36416954, 2023). "Recently, human clinical trials involving FGF23-related hypophosphatemic diseases patients—X-linked hypophosphatemic rickets (XLHR) and Tumor-induced osteomalacia (TIO)—receiving a fully human recombinant IgG1 monoclonal antibody anti-FGF23 (burosumab) is ongoing." (PMID 30087898, 2018). "Involvement of FGFR in the Pi-evoked signal transduction is interesting because enhanced FGFR signaling in osteoblasts/osteocytes might be responsible for the overproduction of FGF23, a key molecule in phosphate homeostasis, in a mouse model for human X-linked hypophosphatemic rickets (XLH)." (PMID 30972027, 2019). "Studies into rare genetic disorders, such as X-linked hypophosphatemic rickets (XLH), have identified a family of proteins, FGF23, PHEX, and MEPE which act through a bone-kidney axis to modulate phosphate homeostasis and thus bone mineralization indirectly." (PMID 22766095, 2012). "Data from tumor-induced osteomalacia (TIO), familial tumoral calcinosis (FTC), and X-linked hypophosphatemic rickets studies have demonstrated the role of FGFR1 and its ligand FGF23 in tightly regulating phosphate balance in conjunction with the parathyroid hormone." (PMID 34199304, 2021). "Inappropriately high FGF23 signaling and resulting chronic hypophosphatemia are associated with disorders of FGF23 excess such as tumor-Induced osteomalacia (TIO) in adults and X-linked hypophosphatemic rickets (XLH) in children, associated with fatigue, muscle weakness, fractures, and pain." (PMID 41473314, 2025). "Moreover, in prior work, we found that a 7.8-fold increase in FGF23 in Hyp mice (a model of X-linked hypophosphatemic rickets in humans) did not alter the fetal serum phosphorus, amniotic fluid phosphorus, or placental phosphate transport." (PMID 38577520, 2024).
atrial fibrillation (40 papers, 2013 to 2026). A disorder characterized by an electrocardiographic finding of a supraventricular arrhythmia characterized by the replacement of consistent P waves by rapid oscillations or fibrillatory waves that vary in size, shape and timing and are accompanied by an irregular ventricular response. "Elevated plasma levels of FGF23 have been associated with a higher incidence of atrial fibrillation and left ventricular dysfunction." (PMID 41426862, 2025). "A few publications indicate also that there is a significant association between FGF23 concentrations and the most common cardiac arrhythmia, atrial fibrillation (AF)." (PMID 34055103, 2021). "Similar to our study, these authors found FGF23 to be higher in HFpEF compared with controls and to be associated with plasma NT‐proBNP levels and more prevalent atrial fibrillation." (PMID 32935918, 2020). "Moreover, prevalent atrial fibrillation was associated with elevated FGF-23 levels, while the presence of coronary artery disease was not." (PMID 40346324, 2025). "In patients with CKD, Klotho deficiency may increase the cardiac toxicity of FGF23 and promote cardiomyocyte aging, thereby favoring the incidence of atrial fibrillation." (PMID 41426862, 2025). "Cardio‐specific FGF23 knockout mitigates susceptibility to ISO‐induced atrial fibrillation." (PMID 40126903, 2025). "This might go some way to explain the clinical data showing that higher systemic FGF-23 levels are associated with a higher incidence of atrial fibrillation." (PMID 35216382, 2022). "Interestingly, FGF23 was also associated with lower left atrial (LA) total emptying fraction which suggests that FGF23 may cause LA-specific cardiac damage and therefore increase susceptibility to atrial fibrillation (AF)." (PMID 40944787, 2025). "We employed linear and Cox proportional hazards regression models to investigate the association between FGF-23 and LVH, all-cause mortality, atrial fibrillation (AF), or congestive heart failure (CHF)." (PMID 38939808, 2023). "Most previously published reports on the cardiac effects of FGF23 have focused on its structural role based on hypertrophy development and on rhythm alterations almost restricted only to atrial fibrillation." (PMID 35042527, 2022). "FGF-23 can increase the incidence of atrial fibrillation (AF) by inducing left ventricular hypertrophy and diastolic and left atrial dysfunction." (PMID 35162472, 2022). "We observed a higher concentration of FGF-23 in the group with atrial fibrillation compared with those having sinus rhythm (atrial fibrillation: 7416 pg/mL; sinus rhythm: 2919 pg/mL; p = 0.049)." (PMID 35159318, 2022). "We also found a relationship between the circulating level of the biomarker FGF-23 and atrial fibrillation." (PMID 35159318, 2022). "Similar to CRE, FGF-23 levels have been previously reported to increase with decreased renal function in patients with atrial fibrillation." (PMID 34497820, 2021). "FGF-23 has been related to heart rate disturbances causing arrhythmias, which can be classified as extra beats, supraventricular tachycardia including atrial fibrillation (AF), ventricular arrhythmias and bradyarrhythmias." (PMID 33767635, 2021). "Studies have also shown that FGF-23 induces atrial fibrosis in patients with atrial fibrillation by increasing reactive oxygen species (ROS) production and subsequently activating signal transducer and activator of transcription 3 (STAT3) and SMAD3 signaling." (PMID 34497820, 2021). "The mechanism of FGF23-induced atrial fibrillation has been demonstrated in pulmonary vein cardiomyocytes of which the ectopic activity is the most important trigger of atrial fibrillation." (PMID 30200452, 2018). "However, this study exclusively involved male mice in animal experiments, leading to a lack of in‐depth discussion on gender differences when discussing the mechanism of cardiac FGF23 on the occurrence of atrial fibrillation." (PMID 40126903, 2025).
atrial fibrillation (continued). "It was speculated that FGF-23/FGFR4 pathway may play an important role in promoting atrial fibrillation by atrial fibrosis." (PMID 33748139, 2021). "Interestingly, in atrial fibrillation, FGF23 mediated profibrotic response via Stat3 and Smad pathways in cardiac fibroblasts, and CEBP-β was significantly upregulated in myocardial tissue of patients on dialysis, which showed enhanced LVH and LV fibrosis." (PMID 31540546, 2019). "A strong independent association between FGF23 levels and atrial fibrillation have been demonstrated in both CKD and non-CKD populations." (PMID 30200452, 2018). "Numerous studies have shown a relationship between FGF23 concentration and atrial fibrillation (AF)." (PMID 36909314, 2023). "This study investigated the effects of high-intensity interval training (HIIT) and moderate aerobic training (AT) on FGF23, Klotho, mineral metabolism, apoptosis markers (BAX, Bcl2), and atrial fibrillation (AF) in a rat CKD model." (PMID 42072635, 2026). "A total of 39 of 51 patients with rheumatic heart disease had persistent atrial fibrillation, the expressions of FGF-23 and FGFR4 were increased in patients with atrial fibrillation, which were positively correlated with atrial fibrosis." (PMID 33748139, 2021). "FGF-23 combined with FGFR4 produced ROS, activated downstream STAT3 and Smad3 proteins, and stimulated expression of matrix metalloprotein-2 (MMP-2) in myocardial tissue of patients with atrial fibrillation, leading to myocardial fibrosis." (PMID 33748139, 2021). "We measured heart weight, blood levels of FGF23, Klotho, and mineral metabolism markers, as well as the heart expression of apoptosis proteins (i.e., BAX, Bcl2) and atrial fibrillation (AF)." (PMID 42072635, 2026).